SMARCA4 (SWI/SNF related BAF chromatin remodeling complex subunit ATPase 4)
Diseases named in the same sentence as SMARCA4 in open-access papers (continued):
Sharing a sentence is not in itself a finding about the gene and the disease.
tumor (continued). "A TCGA pan-cancer meta-data analysis suggested that SMARCA4 does not consistently function as a tumor suppressor across various cancer types." (PMID 34771636, 2021). "Among the remaining 4 SWI/SNF‐deficient UEC, 1 of 3 SMARCA4‐deficient tumors, and 1 SMARCB1‐deficient tumor were MMR‐deficient and none of the reported cases of SMARCA4‐deficient rhabdoid uterine sarcoma occur in a MMR protein‐deficient context." (PMID 33125840, 2021). "Consistent with our in vitro data, SMARCA4 restoration does not significantly suppress H1299 tumor grow but leads to drug resistance to palbociclib treatment compared to the control tumors." (PMID 30718506, 2019). "Further, our data highlight SMARCA4 as a universal vulnerability of SMARCA2-deficient cancer cells, irrespective of the tumor type." (PMID 31406271, 2019). "Of the 32 datasets with highly significant changes (P ≤ 0.0001 and |lineal fold change (FC)| ≥ 2), 26 (81%) presented higher levels of SMARCA4 transcript in tumor samples than in non-tumor samples." (PMID 29391527, 2018). "Levels of SMARCA4 transcript were significantly higher in tumors than in normal tissue for 11 tumor types, and either unchanged or not quantifiable (due to lack of normal samples) in a further 10 tumor types." (PMID 29391527, 2018). "With mutations in genes encoding SWI/SNF subunits (for example, ARID1A, ARID1B, ARID2, PBRM1, SMARCA4 and SMARCB1) collectively occurring in ∼20% of all tumours whose genomes have been characterized to date, SWI/SNF complexes are the most commonly mutated chromatin modulators in human cancer." (PMID 28262751, 2017). "We did not identify a second alteration of SMARCA4 in the tumor DNA by NGS or OncoScan analysis." (PMID 41168858, 2025). "Finally, tumor SP‐06 presented genetic alterations in genes NF2, SMARCA4, and NRAS, which may point to other tumor entities." (PMID 37798904, 2024). "Thus, SMARCA4’s role as a tumor suppressor is not its only role in cancer, and SMARCA4 has also been found to be an oncogene." (PMID 39697230, 2024). "The identified SMARCA4-UT cell lines show a high level of MHC antigen presentation genes, suggesting that they may be immune-responsive tumours, even considering that clinical reports indicate that these tumours respond to ICB." (PMID 39215193, 2024). "Despite no changes in tumor growth in the SCLC-A xenografts, western blot and IHC analysis of tumors confirmed on-target drug activity of AU-24118 as indicated by efficient loss of SMARCA4, SMARCA2, and PBRM1." (PMID 38328238, 2024). "In addition, the tumor cells showed retained INI-1, BRG1/SMARCA4, and SDHB stainings." (PMID 37041531, 2023). "The reintroduction of ATPase-deficient SMARCA4 in SCCOHT cell lines restores complex localization to a few enhancers and promoters, but does not promote tumor-suppressive gene expression programs, suggesting that the catalytic activity is essential for mediating these functions." (PMID 37093326, 2023). "NEC-like IDH2 and NEC-like SMARCA4/ARID1A tumors also demonstrated strong overexpression of proteins specific for neurons or cells of the diffuse neuroendocrine system such as UCHL1, CRMP1 and ENO2, strongly indicating a neuroendocrine differentiation for both tumor classes." (PMID 36443295, 2022). "The SMARCA4 locus revealed no deletions in any of the examined tumor samples." (PMID 33331994, 2021). "Genomic studies performed in cancer patients and tumor-derived cell lines have identified a high frequency of alterations in components of the mammalian switch/sucrose non-fermentable (mSWI/SNF or BAF) chromatin remodeling complex, including its core catalytic subunit, SMARCA4." (PMID 33144586, 2020).
tumor (continued). "None of the patients showed SMARCA4 loss; one patient was positive for BCOR (80% of tumor cells)." (PMID 32972432, 2020). "This is, therefore, not consistent with a general role of SMARCA4 as a tumor suppressor." (PMID 29391527, 2018). "However, this tumor is not always diagnosed in a straightforward manner, as SMARCA4-UT may mimic other malignancies and IHC features may be misinterpreted." (PMID 38542211, 2024). "Thus, SMARCD3 may not have a robust impact on early tumor initiation, although its restricted ductal expression in the normal mouse pancreas (as opposed to the ubiquitous expression of SMARCA4) suggests a potential role in ductal fate." (PMID 36653361, 2023). "Thus, this case may be a tumor, such as a borderline lesion between SMARCA4-DTS and SMARCA4-dNSCLC." (PMID 35151345, 2022). "(k) Expression of SMARCA4, meassured as the sum of all annotated transcripts per milion (TPM; y-axis), for tumours with biallelic LOF and no LOF (x-axis)." (PMID 36883553, 2023). "Only for five genes, namely KAT2A, SMARCA4, BAZ1A, ATAD2 and TRIM28, we observed consistently higher levels and for two genes—KAT2B and SMARCA2—lower levels, respectively, regardless of the tumor type." (PMID 35049055, 2022). "In view of this, tumor tissue may be limited to a long list of investigations, and incorporating multiple IHC marker panels may not be practical; therefore, identification of SMARCA4 among the panel of other genetic markers of interest through NGS-based strategies may be more ideal." (PMID 34440689, 2021). "For two of the 16 tumours mislabelled as non-SCCOHT, SMARCA4 expression was retained and thus would not have improved local diagnostic accuracy." (PMID 31844183, 2020). "Despite no changesin tumor growth in the SCLC-A xenografts, immunoblotting and IHC analysis oftumors confirmed on-target drug activity of AU-24118 as indicated by efficientloss of SMARCA4, SMARCA2, and PBRM1." (PMID 39029462, 2024). "Furthermore and unlike the other tested subunits of the SWI/SNF complex, SMARCA4 and SMARCE1 were homogeneously affected, that is, discovered in every tumor sample of a primary tumor each in two cases, respectively." (PMID 36916408, 2023). "Mechanistically, it has been suggested that both concurrent or nonconcurrent deletion of SMARCA4 and SMARCA2 could further accelerate the process of poor tumor differentiation and EMT." (PMID 35289322, 2022). "First, as a single-case report, the insights generated are descriptive and hypothesis-generating; the favorable treatment response observed may not be generalizable to all SMARCA4-DNSCLC and could be influenced by the unique biology of this tumor or the multi-modal therapy itself." (PMID 41395620, 2025). "Although we were not able to include tumors from this class in our proteomics study due to insufficient quantities of tumor tissue, we did not detect immunohistochemical expression of the neuroendocrine and neuronal markers that were upregulated in NEC-like IDH2 and NEC-like SMARCA4/ARID1A tumors." (PMID 36443295, 2022). "Furthermore, immune infiltration analysis of SMARCA4 reveal a negative correlation CD8+ T cells and SMARCA4 expression in the tumors of ESCA, PAAD, SKCM, and SKCM-metastasis, while the correlation of SMARCA4 and CD8+ T cells in other tumor types still needs further investigation." (PMID 34675941, 2021).
cancer (487 papers, 2009 to 2026). A tumor composed of atypical neoplastic, often pleomorphic cells that invade other tissues. "Carriers of pathogenic SMARCA4 variants face an elevated cancer risk, in the form of rhabdoid tumor predisposition syndrome type 2." (PMID 41528496, 2026). "For example, SMARCA4 mutant cancers become highly addicted to SMARCA2 function since the enzyme compensates for functional SMARCA4 loss in the ATPase module across all BAF complexes." (PMID 40181550, 2026). "Exploiting synthetic lethal interactions caused by specific mutations offers more promise, as in SMARCA4‐mutant cancers reliant on SMARCA2 or SMARCB1‐mutant tumors vulnerable to ncBAF‐targeting." (PMID 40181550, 2026). "This study expands the known anatomical distribution and histological spectrum of SMARCA4-deficient H&N carcinomas." (PMID 41803273, 2026). "We identified eight cases of SMARCA4-deficient H&N carcinomas from the authors' files and reviewed their clinicopathological features." (PMID 41803273, 2026). "This review aims to consolidate the available literature on SMARCA4-deficient carcinomas of the small intestine, highlighting their clinical, histopathological, molecular, and therapeutic features." (PMID 41744871, 2026). "Design: A systematic review of PubMed was conducted through March 2025 to identify all published cases of primary SMARCA4-deficient carcinomas of the small intestine." (PMID 41744871, 2026). "Histologically, immunohistochemical analysis confirmed complete SMARCB1 or SMARCA4 loss (complete in carcinomas and partial in TCS), diffuse CK positivity, and high Ki-67 indices." (PMID 42074742, 2026). "Supporting a central role of these genes in tumorigenesis, mice genetically engineered to express inactivated Smarca4, Arid1a, Smarcb1, or Pbrm1 alleles are prone to cancer." (PMID 41387924, 2025). "We show that treatment with CBP/p300 dual inhibitors causes synthetic lethality in cBAF-deficient cancers such as SMARCA4/SMARCA2-deficient and SS18–SSX fusion cancers." (PMID 39625239, 2025). "The pathological diagnosis concluded a malignant tumor in the right occipital lobe, consistent with metastatic SMARCA4-deficient carcinoma, likely originating from SMARCA4-DNSCLC based on morphology and immunohistochemistry." (PMID 41395620, 2025). "SMARCA4/2 deficiency reportedly restricts the flow of calcium ions mediated by IP3R3 from cancer cells to the mitochondria, leading to resistance to chemotherapeutic drugs." (PMID 41170461, 2025). "In a Phase I (NCT05639751) study investigating the novel SMARCA2 degrader PRT3789, patients with advanced cancers harboring SMARCA4 deficiency were treated to evaluate safety and efficacy." (PMID 41049269, 2025). "Loss-of-function mutations or deficient expression of SMARCA4 have been increasingly recognized as a hallmark of a subset of highly aggressive cancers, often with poor prognosis and limited therapeutic responsiveness." (PMID 40867304, 2025). "The sensitivity of SMARCA4-deficient cancer cell lines to CBP/p300 dual inhibitors was similar to that of SWI/SNF WT cell lines." (PMID 39625239, 2025). "The association between SMARCA4 abnormalities and undifferentiated histology has been reported in other cancer types." (PMID 40866717, 2025). "In this study, we reviewed over 100 published reports of patients with SMARCA4-deficient cancers to gain a deeper understanding of their characteristics, treatment options, and survival outcomes." (PMID 40867304, 2025). "Research on SMARCA4 variants from targeted exome sequencing in various cancers found that missense mutations were most frequent overall, while truncating mutations were more common in NSCLC and CUP than in other tumors." (PMID 40866717, 2025). "SMARCA4 (SWI/SNF related BAF chromatin remodeling complex subunit ATPase 4)-deficient undifferentiated uterine sarcoma (SDUS) is a newly recognized malignant neoplasm of mesenchymal derived from the uterus." (PMID 40826772, 2025).
cancer (continued). "Among them, roughly one-third achieved either partial response or stable disease, aligning with the emerging evidence of immunotherapy sensitivity in SMARCA4-deficient cancers." (PMID 40867304, 2025). "Over half of the SMARCA4 mutations in human cancer samples are missense mutations that tend to cluster in the catalytic domain, at subunit–subunit interaction interfaces, and at nucleosome binding sites." (PMID 41387924, 2025). "The loss of SMARCA4 enhances tumorigenesis by promoting genomic instability, thereby acting as a key driver of cancer development." (PMID 40416876, 2025). "Background/Objectives: SMARCA4-deficient or SMARCA4-mutated cancers are rare but highly aggressive tumors with poor differentiation, resistance to conventional treatments, and limited clinical guidance." (PMID 40867304, 2025). "Both drugs’ development is based on the same scientific principle: SMARCA4 is frequently mutated in multiple cancers, including up to 10% of NSCLC." (PMID 41049269, 2025). "Regarding survival, the literature on various cancer types suggests a link between SMARCA4 mutations or loss of function and poor prognosis." (PMID 38610978, 2024). "For example, SMARCA4-deficient cancer cells lose tumorigenicity and undergo cell cycle arrest and senescence upon the depletion of SMARCA2." (PMID 38390898, 2024). "SMARCA4 loss-of-function mutations have been observed in different human cancers, such as lung, gastric, breast, ovarian, pancreatic, prostate, and hematological cancers." (PMID 39580422, 2024). "Thoracic SMARCA4-deficient undifferentiated tumor (SMARCA4-UT) is a high-grade malignant neoplasm with a poor prognosis." (PMID 39497014, 2024). "Such discoveries powerfully support the potential of SMARCA2 as a valuable target for developing therapies to treat cancers deficient in SMARCA4." (PMID 38675453, 2024). "To date, we examined 54 SMARCA4 mutation patterns in 41 SCCOHT cases from the Catalog of Somatic Mutations in Cancer (COSMIC) database." (PMID 38903333, 2024). "Inactivation of SMARCA4 is associated with various cancer types such as lung, brain, ovarian, and pancreatic cancer." (PMID 39439958, 2024). "SMARCA4 and SMARCA2 have emerged as oncogenic dependencies in certain cancer types, with SMARCA4 specifically being implicated in cancer metastasis." (PMID 39174852, 2024). "SMARCA4 (BRG1)-deficient carcinoma in the head and neck is a rare and highly aggressive malignant tumor that is advanced at diagnosis, prone to invasion of adjacent structures, difficult to operate on, and has a poor prognosis." (PMID 38989233, 2024). "Thoracic SMARCA4-UT has been defined as a new entity of a rare high-grade malignant neoplasm that displays a deficiency of SMARCA4 (BRG1)." (PMID 38374950, 2024). "The study successfully demonstrated the targeted degradation of SMARCA2 over SMARCA4 and observed the therapeutic effectiveness in cancer models with SMARCA4 deficiency." (PMID 38389844, 2024). "Studies have shown that mutations in SMARCA4 are observed in a wide variety of cancer types, highlighting its broad impact on oncogenesis." (PMID 38610978, 2024). "SMARCA4 gene expression was strongly associated with gene expression related to immunity in various cancers." (PMID 39125664, 2024). "Different patients of SMARCA4 (BRG1)-deficient carcinoma in the head and neck respond differently to radiotherapy and chemotherapy." (PMID 38989233, 2024). "Little is known about the invasion of the middle cranial fossa in SMARCA4 (BRG1)-deficient carcinomas." (PMID 38989233, 2024). "SMARCA4-deficient carcinomas in the head and neck are poorly reported in the literature, most of which are case reports." (PMID 38989233, 2024). "The majority of SMARCA4-deficient carcinomas develop in the nasal cavity, and they involve multiple sinonasal sites in a subset of cases." (PMID 38491228, 2024).
cancer (continued). "Overall, the pathologic findings were consistent with a poorly differentiated carcinoma with SMARCA4 deficiency." (PMID 38656564, 2024). "The similarities between cases 2 and 1 were that both SMARCA4-deficient carcinomas invaded the skull base, and both were male patients with a history of smoking." (PMID 38989233, 2024). "They should also consider SMARCA4 (BRG1)/SMARCB1-deficient carcinoma as a possible diagnosis to expand their diagnostic options." (PMID 38989233, 2024). "Posthumous histopathological exam of the esophageal biopsies was consistent with undifferentiated SMARCA4-deficient carcinoma." (PMID 38656564, 2024). "SMARCA4 (BRG1)-deficient carcinomas are a rare group of highly aggressive tumors that can occur in multiple sites, such as the nasal cavity, paranasal sinuses, thorax, lungs, gastrointestinal tract, and ovaries." (PMID 38989233, 2024). "Further, the authors report that HER2 (ERBB2) gene amplification was observed in 5 (12%) of 42 carcinomas with pathogenic SMARCA4 mutation." (PMID 38656564, 2024). "Posthumous histopathology consistent with undifferentiated SMARCA4-deficient carcinoma of the esophagus." (PMID 38656564, 2024). "SMARCA4 (BRG1)-deficient carcinomas in the head and neck are a rare and highly aggressive group of malignant tumors." (PMID 38989233, 2024). "SWI/SNF-complex-deficient malignancies can be determined by immunohistochemical staining with INI1 antibody for SMARCB1-deficient and BRG1 antibody for SMARCA4-deficient carcinomas." (PMID 38491228, 2024). "These included ARID1B, the paralog of which, ARID1A, is among one of the most frequently mutated genes in cancer, SMARCA4, and SMARCA2." (PMID 37500730, 2023). "Mirroring the effects of inhibitors targeting Complex I and glutaminase or glutamine deprivation, alanine supplementation selectively suppressed OXPHOS in SMARCA4/2-deficient cancer cells." (PMID 37210563, 2023). "It has been shown to degrade SMARCA2 and SMARCA4 in various cancer cells, deplete SMARCA2 in SMARCA4-mutant AML, and cause decreased cell proliferation and cell death." (PMID 36770884, 2023). "Together, our findings show that GLUT1 downregulation is a unique feature of SMARCA4/2-deficient cancers." (PMID 37210563, 2023). "Herein, we report two rare cases of GI NEC with SMARCA4 deficiency and provide insight into the clinicopathological features of this highly aggressive malignant tumor." (PMID 38090508, 2023). "We have identified the crucial role of Smarca4 in regulating tubular cell differentiation and the expression of the cancer-causing gene Pttg1 in the kidney." (PMID 37727504, 2023). "Together, these data show that SMARCA4/2-deficient cancer cells depend on elevated SLC38A2 for glutamine uptake and metabolism to sustain the TCA cycle." (PMID 37210563, 2023). "Our data indicate that SMARCA4/2-deficient cancer cells rely on glutamine uptake as an alternative carbon source fueling the TCA cycle." (PMID 37210563, 2023). "SMARCA4/2-deficient cancers remain difficult to treat as they rarely harbor known druggable mutations and are resistant to conventional chemotherapies." (PMID 37210563, 2023). "Alanine supplementation induced dosage-dependent growth suppression in SMARCA4/2-deficient cancer cells but had little or mild effect in proficient controls." (PMID 37210563, 2023). "Nevertheless, our data support that the GLUT1 deficiency induced by SMARCA4/2 loss is a key contributor to the OXPHOS dependency in these SMARCA4/2-deficient cancer cells." (PMID 37210563, 2023). "These missense mutations are some of the most frequently reported SMARCA4 mutations across all cancers." (PMID 37433987, 2023). "Cancer cells deficient in either SMARCA4 or SMARCA2 are vulnerable to genetic ablation of the remaining paralog, a synthetic lethality that is being explored as a potential therapeutic strategy." (PMID 37210563, 2023).